IRF5 (interferon regulatory factor 5)
Diseases named in the same sentence as IRF5 in open-access papers (continued):
Sharing a sentence is not in itself a finding about the gene and the disease.
autoimmune disease (75 papers, 2008 to 2025). A disorder resulting from loss of function or tissue destruction of an organ or multiple organs, arising from humoral or cellular immune responses of the individual to their own tissue constituents. "Highly expressed in monocytes, macrophages, B-cells, and dendritic cells, IRF5 was implicated in various inflammatory and autoimmune diseases." (PMID 38999981, 2024). "IRF5 polymorphisms have been well described for autoimmune disease and are often associated with various levels of inflammation." (PMID 37227774, 2023). "In genome-wide association studies (GWAS), variants at the IRF5 locus have been associated with autoimmune diseases (systemic lupus erythematous, rheumatoid arthritis, multiple sclerosis)." (PMID 37978231, 2023). "GWAS have reported that the IRF5 locus is associated with autoimmune diseases and with the estimated glomerular filtration rate (eGFR)." (PMID 37978231, 2023). "This elaborate regulation of IRF5 promoter usage leads to increases in both IRF5-short transcripts and ensemble gene expression of IRF5, ultimately resulting in monocyte/macrophage dysfunction and high autoimmune disease risk." (PMID 36869052, 2023). "Polymorphisms in the IRF5 gene have been associated with an increased risk of numerous autoimmune diseases, including SLE, primary Sjögren syndrome, and rheumatoid arthritis." (PMID 36814288, 2023). "Here the authors used an evidence-based strategy to prioritize causal pleiotropic variants of autoimmune diseases, and revealed that rs4728142 modulates aberrant IRF5 alternative promoter usage by ZBTB3-mediated chromatin looping." (PMID 36869052, 2023). "On the other hand, our gene-based eQTL and colocalization results showed that rs4728142-A was significantly associated with higher IRF5 gene expression and obtained a shared genetic effect with autoimmune disease risk." (PMID 36869052, 2023). "We found a dramatic reduction in the number of GC B cells prior to the onset of overt autoimmune disease in the mice with heterozygous deficiency of IRF5 in B cells." (PMID 34197340, 2021). "The IRF5 polymorphisms associated with an increased risk of developing SLE and other autoimmune diseases are in the noncoding region of the IRF5 gene and show some association with increased IRF5 expression and/or functional change." (PMID 34197340, 2021). "IRF5 has also gained some attention in recent years for its involvement in autoinflammatory and autoimmune diseases, and much like IRF1, it has been implicated in induced cell death." (PMID 34685580, 2021). "We analyzed a cohort of 305 ME/CFS patients and 201 healthy controls for potential disease association of the PTPN22, CTLA4, TNF, and IRF5 SNPs that were described to be risk loci for various autoimmune diseases." (PMID 32328064, 2020). "Recently, we identified a functional SNP, associated with 2 autoimmune diseases, that exerted allele-specific enhancer regulation on IRF5 expression through long-rang loop formation." (PMID 32879140, 2020). "IRF5 regulatory axis shapes the phenotype of newborn macrophages and plays an important role in systemic inflammation, as IRF5-deficient mice are protected from LPS-induced systemic inflammation and autoimmune diseases." (PMID 30050534, 2018). "In the last 10 years, numerous studies have reported the association of IRF5 polymorphisms with autoimmune disease susceptibility." (PMID 30515152, 2018). "The transcription factor interferon regulatory factor 5 (IRF5) is one such candidate as polymorphisms in IRF5 associate with risk of numerous autoimmune diseases and correlate with elevated IRF5 expression." (PMID 29367853, 2017). "We investigated a panel of genes previously shown to be linked with GD as well as genes associated with other autoimmune diseases (e.g., IRF5 and TLR4)." (PMID 27014188, 2016). "IRF5’s function (or dysfunction) in autoimmune disease and cancer is tightly linked to its expression." (PMID 27481535, 2016).
autoimmune disease (continued). "Studies here grew out of GWAS showing that IRF5 was associated with SSc and other autoimmune diseases that increase heart disease and our knowledge that 4F inhibited IRF5 in Tsk/+ mice." (PMID 27050551, 2016). "Overexpression of IRF5 is associated with susceptibility of autoimmune diseases, including systemic lupus erythematous, rheumatoid arthritis and multiple sclerosis." (PMID 26578562, 2015). "Despite an increasing body of evidence suggesting that genetic variants in IRF5 are linked to enhanced susceptibility to the autoimmune disease SLE, a comprehensive functional characterization of these variants is still missing." (PMID 25084355, 2014). "In recent decades, a number of studies had indicated IRF5 gene displayed a strong association with varied autoimmune diseases." (PMID 25337792, 2014). "Interferon regulatory factor 5 (IRF5) contains polymorphisms associated with these autoimmune diseases." (PMID 24223576, 2013). "The interferon regulatory factor 5 (IRF5) gene occupies a prominent place among the genetic factors involved in susceptibility to rheumatic and autoimmune diseases." (PMID 23941291, 2013). "IRF5 has been shown to respond to TLR and NOD signaling, and polymorphisms of IRF5 are associated with increased risk of autoimmune disease." (PMID 22412986, 2012). "IRF5 has been shown to be strongly associated with certain autoimmune diseases in different ethnic populations and to play a critical role in the pathogenesis of autoimmunity." (PMID 19816589, 2009). "Polymorphisms in IRF5 have been linked to a heightened risk of developing autoimmune diseases." (PMID 40137979, 2025). "Remarkably, prior studies have reported that the IRF5 risk haplotypes in autoimmune diseases lack B cell-intrinsic effects and alternatively could exert prominent effects in human monocyte-derived cells." (PMID 36869052, 2023). "Interestingly, for many of these autoimmune diseases, polymorphisms in the IRF5 gene are associated with disease severity, including SLE, SS, and RA." (PMID 34065953, 2021). "Based on two “omics” approaches, NXF1 was identified as one of the IRF5 signaling pathway regulators, and in turn genome-wide association studies have implied the association of IRF5 with several autoimmune diseases, including SLE, Sjogren’s syndrome, inflammatory bowel disease, and MS." (PMID 34065644, 2021). "Polymorphisms in the IRF5 gene have been associated with the susceptibility to autoimmune diseases." (PMID 32517705, 2020). "Here, we hypothesized a role for IRF5, since this transcription factor is known to be involved in enhancing TNF transcription, is highly expressed in human myeloid APCs, and since IRF5 polymorphisms are a known risk factor for several autoimmune diseases." (PMID 31024565, 2019). "Thus, it is possible that IRF5 risk haplotype is linked to the enhanced production of Tfh-promoting cytokines in subjects with autoimmune diseases traits." (PMID 30061896, 2018). "In addition, genetic polymorphisms in human IRF5 that lead to the expression of various unique isoforms or higher expression of Irf5 mRNA have been linked to autoimmune diseases, including MS." (PMID 29973381, 2018). "We intend to examine the genetic contribution of TNFAIP3, IFIH1, and IRF5 to PM/DM based upon the postulated roles of each of these genes' products in innate and cell-mediated immunity in PM/DM and their described associations with autoimmune diseases." (PMID 25337792, 2014). "The IRF5 gene contains several GWAS-identified polymorphisms associated with autoimmune diseases." (PMID 24223576, 2013). "Additionally, several genetic studies have identified IRF5 genetics variants associated with an increased risk of several autoimmune diseases." (PMID 24116155, 2013).
autoimmune disease (continued). "Other autoimmune diseases such as rheumatoid arthritis, Sjogren's syndrome, systemic sclerosis, multiple sclerosis, and inflammatory bowel disease have also been associated with IRF5 polymorphisms, suggesting a role of IRF5 in common autoimmune disease pathways." (PMID 23251221, 2012). "Moreover, IRF5 polymorphisms are implicated in several autoimmune diseases." (PMID 31178872, 2019). "Interestingly, IRF5 risk alleles that associate with asthma were found to be almost completely opposite to those for autoimmune disorders, supporting potentially distinct roles for IRF5 in the pathogenesis of asthma and autoimmune disorders." (PMID 30515152, 2018). "IRF5 is determinant to promote disease development in a murine model of lupus erythematosus autoimmune disease." (PMID 40137979, 2025). "In various autoimmune diseases, including rheumatoid arthritis and SLE, excessive IRF5 activation is closely linked to dysregulated inflammatory responses." (PMID 41383611, 2025). "The transcription factor interferon regulatory factor 5 (IRF5) is a central mediator of the host immune response to pathogens and is implicated in the pathogenesis of many inflammatory and autoimmune diseases." (PMID 38969706, 2024). "Studies have identified Lyn as an interferon regulatory factor 5 (IRF5) binding protein to regulate the TLR‐MyD88‐IRF5 pathway in mice suffering from autoimmune disease." (PMID 37132040, 2023). "Autoimmune-risk haplotypes exhibit higher IRF5 levels and are associated with increased levels of pro-inflammatory cytokines, suggesting that expression of IRF5 in B cells contributes to the development of autoimmune diseases." (PMID 36814288, 2023). "For example, Asian-specific haQTLs provided novel candidate variants in gene loci associated with leprosy (SIGLEC5, TNFSF15) and autoimmune disease (CARD9, IRF5, IL27, FOS) (nd 48)." (PMID 35102304, 2022). "The role and relevance of IRF5 in immune cell dysfunction in the context of autoimmune disease and cancer progression has become a hot topic for research in recent years." (PMID 32582209, 2020). "Here we focus on three genes, STAT4, IRF5, and TNFSF4, which are identified and validated as risk loci in GWAS in multiple autoantibody mediated autoimmune diseases with a strong disease association at the genome-wide p value of at least 5 × 10−8." (PMID 30061896, 2018). "Given the importance of IRF5 as a potential biomarker for autoimmune disease and cancer, we evaluated the ability of antibodies to detect IRF5 by immunohistochemical (IHC) and immunofluorescence (IF) microscopy in human splenic tissue." (PMID 27481535, 2016). "Accordingly, IRF5D provides new opportunities for investigators to determine if and the extent to which inhibiting IRF5 is an effective for treating myocardial and vascular disease in autoimmune disease." (PMID 27050551, 2016). "We found that candidate variants at several risk loci are methylation quantitative trait loci (mQTLs), including mQTLs for DENNDIB, PLCL2, IRF5 and TNFRSF1A, all genes that are implicated in risk for other autoimmune diseases." (PMID 26394269, 2015). "Among many autoimmune disease-related genes, STAT4, C8orf13–BLK, as well as interferon regulatory factor 5 (IRF5) seem to be the most representative susceptibility genes in the Japanese population." (PMID 24632671, 2014). "Genetic variation in interferon regulatory factor 5 (IRF5), a major regulator of the type I interferon induction, has been associated with risk of developing several autoimmune diseases." (PMID 24116155, 2013). "Single nucleotide polymorphisms in the genes for IRF5, IRF7 and IRF8 have also been associated with an increased risk for SLE and other autoimmune diseases." (PMID 23826184, 2013). "Since high expression of IRF5 contributes to the development of autoimmune disease, understanding the source of increased IRF5 levels is key to understanding autoimmune etiology." (PMID 24223576, 2013).
autoimmune disease (continued). "Our findings are also the first to show that 4F decreases myocardial expression of IRF5, a transcription factor that others have shown is central to host-defense and inflammation in a variety of autoimmune diseases." (PMID 23251680, 2012). "The IRF5 gene has been associated with SLE in multiple ethnic groups and repeatedly implicated in susceptibility to many autoimmune diseases, becoming a rationale for the focus of our study." (PMID 22909381, 2012). "Single-nucleotide polymorphisms in several transcription factors involved the type I IFN pathway (for example, IRF5, Tyk2, and STAT4) have recently been associated with a number of autoimmune diseases, including SLE and RA." (PMID 20096109, 2010). "Based on the effects of gain-of-function mutations in other autoimmune diseases and the effects of mutations in the IL-10, IL-23, and NOD2 pathways, it appears likely that increased IRF5 expression will affect the response to TLR and Nod-like receptor sensing of bacterial antigens." (PMID 41007813, 2025). "IRF5 is a well-documented transcription factor critical in the regulation of immune responses, particularly in the production of type I interferons, and has been proposed as a therapeutic target for autoimmune diseases." (PMID 41256005, 2025). "CCR6, IRF5, and CD40 are all well-known autoimmune disease genes associated with RA or AS34–37." (PMID 38360850, 2024). "Among the IFN-I signaling pathway genes, a SNP (rs4731532) had an ir-QTL effect for an IRF5 isoform (IRF5_1, unannotated in GENCODE) and was co-localized with GWAS signals linked to a range of autoimmune diseases, including systemic sclerosis, Sjögren’s syndrome, and RA." (PMID 39288763, 2024). "In addition, analysis of RNA-seq data from autoimmune disease patients suggests that IRF5 gene and IRF5-short transcripts show higher expression in RA or SLE patients than healthy individuals." (PMID 36869052, 2023). "However, understanding why rs4728142 and IRF5 display remarkable pleiotropic effects on different autoimmune diseases requires long-term exploration in the future." (PMID 36869052, 2023). "In addition, recent studies have shown that IRF5 regulates proinflammatory M1 macrophage polarization tending towards improving the inflammatory and immune response, contributing to autoimmune disease occurrence and development." (PMID 36869052, 2023). "Whether the observed sex differences in IRF5 contribute to the observed higher prevalence of autoimmune diseases in women needs to be assessed in future studies." (PMID 36814288, 2023). "For instance, the enrichment of certain risk loci in the Mexican Amerindian and MEZ populations, such as the IRF5 TCA risk haplotype, could partly explain the high prevalence of autoimmune diseases in the Mexican population." (PMID 36714151, 2022). "IRF5 expression in bone marrow–derived cells is required for the development of autoimmune disease." (PMID 34197340, 2021). "Our results suggest that HDACi may have therapeutic potential in patients with autoimmune diseases such as SLE through repression of IRF5 expression." (PMID 28525378, 2017). "Moreover, our study provided a new insight into molecular mechanisms whereby the HDAC inhibitor TSA repressed IRF5 expression, and suggested a mechanistic rationale for application of HDACi in the treatment of autoimmune diseases such as SLE." (PMID 28525378, 2017). "However, the regulatory mechanisms by which IRF5 contributes to autoimmune disease pathogenesis are still unclear." (PMID 28578407, 2017). "Notably, chronic IRF5 activation enhances apoptosis, a characteristic feature of cancer as well as autoimmune disorders such as inflammatory bowel disease, lupus erythematosus and scleroderma." (PMID 27050551, 2016). "Although substantial evidence exists linking IRF5 to autoimmune disease and a number of reports suggest IRF5 may be an important therapeutic target for treating autoimmune disease, inhibitors for IRF5 remain lacking." (PMID 27050551, 2016).
autoimmune disease (continued). "Accordingly, IRF5D may be useful for investigating the role of IRF5 in inflammatory and fibrotic heart disease in a variety of autoimmune diseases." (PMID 27050551, 2016). "Accordingly, inhibiting IRF5 may be an effective therapeutic strategy for treating myocardial inflammation and fibrosis in humans with autoimmune disease." (PMID 27050551, 2016). "Primary SS is an autoimmune disease with a genetic basis in which at least 40 gene risk factors may be involved, including BLK, IRF5, STAT4, and the HLA locus." (PMID 26379672, 2015). "As B cells, these cells are relevant to autoimmune disease and express IRF5." (PMID 24223576, 2013). "Furthermore, as emerging studies have highlighted the substantial contributions of Irf5 to autoimmune diseases, neuropathic pain, obesity, and hepatic fibrosis, future research should investigate whether Aff3ir-ORF2 has beneficial effects in these contexts." (PMID 40315012, 2025). "Therefore, targeting IRF5 may not only be an interesting approach to treat chronic inflammation, but also for autoimmune diseases." (PMID 34065953, 2021). "However, continued research into a potential role(s) for IRF5 in the other T cell subsets, particularly follicular helper T (Tfh) cells and regulatory T (Treg) cells, is an important next step in the elucidation of autoimmune disease pathogenesis via IRF5 dysregulation." (PMID 32582209, 2020). "Prior to these findings, IRF5 was identified as a critical mediator of MyD88-dependent TLR signaling, leading to the expression/production of multiple pro-inflammatory cytokines including type I IFNs, IL6, TNFα, IL12, IL23, and others implicated in autoimmune disease pathogenesis." (PMID 30515152, 2018). "Indeed, hyper-activation of IRFs (most notably IRF1, IRF3, IRF5, IRF7, and IRF9) has been implicated in disease pathogenesis as it leads to unrestricted production of IFNs, which is linked to the development of numerous inflammatory and autoimmune diseases." (PMID 30515152, 2018). "Our results strongly suggest that developing specific inhibitors of IRF5 and/or their pathways of activation may result in new therapeutic modalities that would be capable of inhibiting inflammation and oxidative stress in autoimmune disease." (PMID 23251680, 2012). "Persistent activation of IFN-I signaling represents a key pathological basis of multiple autoimmune diseases, primarily driven by aberrant activation of IRFs, particularly IRF3, IRF5, and IRF7." (PMID 41383611, 2025). "In addition, another novel gene, IL2RA interacts with the well-known autoimmune disease genes CCR6, IRF5, and CD40, which are the hub genes in the network." (PMID 38360850, 2024). "A representative example of an autoimmune disease where the use of a pan-IRF inhibitor could be advantageous is SLE, in which combined action of IRF5 and IRF7 has been documented." (PMID 31178872, 2019). "Our study also contributes to the evidence that there might be genes or pathways that are common between multiple autoimmune diseases, and that the type I IFN signalling system, to which the IRF5 gene belongs, is likely to be one of these pathways." (PMID 18285424, 2008). "IRF3, IRF5, and IRF7 were essential for the production of type I interferons (IFNs) upon pathogen recognition by receptors, impacting viral and bacterial infections, inflammatory responses and autoimmune diseases, cancer growth, and metastasis, and changes in the tumor microenvironment." (PMID 38999981, 2024). "Our research indicated that infection, a family history of autoimmune disease in first-degree relatives, negative stressful life events and CGGGG insertion/deletion polymorphisms in the IRF5 gene might be risk factors for pSS." (PMID 36534351, 2023).